IL1B (interleukin 1 beta)
Diseases named in the same sentence as IL1B in open-access papers (continued):
Sharing a sentence is not in itself a finding about the gene and the disease.
diabetes (continued). "Massive cytokine production during chronic inflammation contributes to the interaction of periodontitis and diabetes, with common factors including IL-1β, IL-6, prostaglandin E2 (PGE2), TNF-α production." (PMID 39193343, 2024). "Diabetes was thereby affiliated with the M1 macrophages recruitment and the expression of IL-6 and IL-1B during the IRI procedure." (PMID 39656542, 2024). "Quercetin has been described as reducing MDA and neural nitrite levels, preventing falls in neural SOD and GSH levels following diabetes, and lowering TNFα and IL-1β levels in the sciatic nerve." (PMID 38534744, 2024). "Other studies have shown that in STZ diabetes, there is an increase in pulmonary infiltration with neutrophils and macrophages and an increase in the secretion of proinflammatory cytokines (IL-1β, IL-6)." (PMID 38792932, 2024). "Hesperidin demonstrated neural protective effects, which are evident from decreased neutrophil and macrophage infiltration in the sciatic nerve and decreased mRNA expression of neural TNF-α and IL-1β, two key pro-inflammatory cytokines in diabetes progression." (PMID 39459367, 2024). "IL‐1β levels were statistically significantly higher in diabetes and diabetes +2 mg/kg bW stevia group than in control, 2 mg/kg bW stevia, 25 mg/kg bW stevia, and diabetes +25 mg/kg bW stevia groups (**p < .01)." (PMID 39479688, 2024). "Increased TNF concentrations alongside IFN-γ and IL-1β concentrations were measured in lung homogenates from mice with chronic streptozotocin-induced diabetes (vs. euglycemic mice) which coincided with greater areas of inflammation in the lung tissue." (PMID 39649174, 2024). "RS treatment significantly decreases the levels of proinflammatory cytokines, HbA1c, IL-6, TNF-α, and IL-1β in diabetes in the elderly." (PMID 38903985, 2024). "The keywords used for PubMed were ‘(diabetes OR hyperglycemia OR prediabetes OR insulin resistance OR glucose intolerance) AND (canakinumab OR interleukin-1 beta antagonist)’ in combination with Medical Subject Headings (MeSH) terms." (PMID 39286685, 2024). "We have previously shown that diabetes leads to the activation of caspase-1 and IL-1β production and that blocking downstream caspase-1/IL-1β/IL-1R1 signaling using IL-1R1 knockout mice prevented the formation of acellular capillaries and Müller cell death." (PMID 39483336, 2024). "High expression of NLRP-3, caspase-1, IL-1β and IL-18 was observed in macrophages isolated from wounds of patients with type 2 diabetes mellitus whose wounds lasted for at least 3 months." (PMID 38957662, 2024). "The number of IL1β mRNA-labelling dots clearly indicates that the smooth muscle of the gut wall is also a source of cytokines, although it is less affected in diabetes than the ganglia." (PMID 36982878, 2023). "The administration of cMDSCs propagated from GM-CSF, IL-6, and IL-1β cytokines prolonged the diabetes-free survival of diabetic mice by way of inhibition of activated T cells." (PMID 37296628, 2023). "The results of the study showed that in the GK group (the diabetes model group), serum levels of LPS and Il-1β were significantly increased compared to the NC group." (PMID 37959125, 2023). "These collective results showed that IL-1β was at high expression in diabetes mellitus–periodontitis due to macrophage pyroptosis." (PMID 37047282, 2023). "Allium Sativum plays a role in the treatment of diabetes by enhancing the gene expression of caspase 3 and caspase 9, reducing IL-1β, IL-6, and TNF-α level and increasing IFN-γ in vitro and in vivo." (PMID 37240430, 2023). "Surprisingly, OI treatment of the monocytes attenuated IL-1β production compared with LPS-only stimulation in both non-diabetes and type 1 diabetes participants." (PMID 36918798, 2023). "The deletion of IL-33 enhanced diabetes-induced retinal inflammation, evidenced by upregulated pro-inflammatory cytokine expression (Ccl2, Il1b, Il6, Tnf, Tgfb and Inos), sustained gliosis and microglia activation." (PMID 37671525, 2023).
diabetes (continued). "Administration of a custom-made, rat-specific IL-1β monoclonal antibody to Cohen diabetes-sensitive rat, a genetic model of nutritionally induced diabetes when fed a high-sucrose/low-copper diet, counteracted β-cell dysfunction and glucose intolerance." (PMID 37008937, 2023). "In diabetics, the number of IL1β mRNA dots increased by a lesser extent in intestinal smooth muscle as well, and this change was significant in the duodenum and colon (p < 0.05)." (PMID 36982878, 2023). "This study showed that 12 weeks of oral treatment of TRF in rats with STZ-induced diabetes reduces expression of the markers of retinal inflammation including IL-1β, IL-6, TNF-α, IFN-γ, MCP-1, and iNOS." (PMID 37268913, 2023). "Similar activity and decreased levels of TNF-α, IL-1β, and IL-6 in serum were reported for fucoidan isolated from Saccharina japonica in a model of streptozotocin-induced diabetes mellitus in rats after 4 weeks of treatment." (PMID 37760952, 2023). "The clinical (BOP) and glucose parameters (fasting glucose levels, and HbA1c) were statistically higher in the diabetes group; moreover, RNAm levels of IL-1β, TNF-α, and NF-kB were higher when compared to healthy controls." (PMID 36832168, 2023). "Chronic inflammation induced by diabetes is related to the excretion of proinflammatory cytokines like IL-1β, which exacerbates nerve damage, induces microvascular complications of diabetes, and disturbs the regulation of cardiovascular system." (PMID 36660202, 2023). "This is also confirmed by our observation of high expression of IL-1β and aggravated destruction of periodontal tissues in rats with diabetes mellitus–periodontitis." (PMID 37047282, 2023). "The same outcome was obtained when the authors used the caspase-1/IL-1β pathway to prevent diabetes-induced MC death in vivo." (PMID 37418795, 2023). "The sustained diabetes-evoked inflammatory responses mediated by pro-inflammatory modulators (IL-1β, TNF-α) majorly contribute to the development of DR, consequently altering the retinal structure and impairing its function." (PMID 37032781, 2023). "Therapeutic inhibition of the NLRP3/IL-1β system protected mice from air pollution-induced diabetes and thus points towards potential therapeutic strategies." (PMID 37400850, 2023). "Four models were evaluated where either baseline LVEF, IS, MVO or IMH were regarded as the dependent variable, and GSDMD, IL-1β, CtnI, diabetes, CRP and anterior infarction localization as independent variables." (PMID 37424923, 2023). "Macrophage pyroptosis drives the secretion of IL-1β, which has been recently reported to be a featured salivary biomarker for discriminating periodontitis in the presence of diabetes." (PMID 37047282, 2023). "In our present study, IL-1β mRNA expression increased significantly in pancreatic tissues of rats with STZ-induced diabetes." (PMID 37375806, 2023). "In our study, diabetes elevated the prefrontal cortex and hippocampal gene expression of NfκB, IL-1β, and IL6, as well as the immunoexpression of TNF-α and GFAP, which are considered indicators of astrocyte activation." (PMID 38105928, 2023). "Prolonged enhanced concentrations of the pro‐inflammatory cytokines IL‐1β and TNFα in blood, and reduced anti‐inflammatory IL‐10 in sputum, have been observed in patients with TB and diabetes comorbidity, in accordance with our results." (PMID 37649224, 2023). "When SGLT2 inhibitors were provided, the same group showed diabetes-associated increases in inflammation-suppressed NLRP3 inflammasome activity as well as lower mRNA levels of ASC, IL-6, IL-1b, TNF-a, and caspase-1." (PMID 37566054, 2023). "Since IL-1β is the major pathological contributor to endothelial dysfunction in diabetes, the anti-inflammatory effects of PCA specific on endothelial cells were further verified by the use of IL-1β-induced inflammation model." (PMID 37025617, 2023).
diabetes (continued). "The inflammatory mediators TNF-α, IL-1β, IFN-γ, iNOS and NF-κB have close association with progression of diabetes." (PMID 36653816, 2023). "Lastly, there was a search done with specific overlaps, such as the role of IL-1b in both diabetes and OA, with specific keywords such as interleukin-1 (IL-1), tumor necrosis factor (TNF) alpha, and oxidative stress." (PMID 37255905, 2023). "By establishing a model of experimental diabetes mellitus–periodontitis in rats, we found that IL-1β and gasdermin D were highly expressed, leading to aggravated destruction of periodontal tissue." (PMID 37047282, 2023). "Diabetes increases inflammation in periodontal tissues, with higher levels of inflammatory mediators such as interleukin-1β (IL-1β) and tumour necrosis factor-α (TNF-α)." (PMID 36981453, 2023). "It activates the inactive forms of pro-inflammatory cytokines IL-1β and IL-18, the over expression of these cytokines promotes several diseases including diabetes mellitus." (PMID 36653816, 2023). "Then at day 7, the end of our observation H2-Aa, H2-Ab1, H2-DMa, H2-DMb1, H2-Eb1, Il1b genes were upregulated in the diabetes group corresponded to type I diabetes and Th17 cell differentiation." (PMID 36445632, 2023). "As a result, many new potential drugs have been studied to observe the "efficacy of targeting IL-1b" in controlling both OA and diabetes." (PMID 37255905, 2023). "Subsequently, factors such as LPS and IL-1β circulate throughout the body, further exacerbating the symptoms of diabetes." (PMID 37959125, 2023). "In the present study, the effect of endurance training on the expression of NLRP3, P38 MAPK, TNF-α, and IL-1β genes in the spinal cord of rats with diabetic neuropathic pain was investigated." (PMID 35655729, 2022). "We observed that pro-inflammatory cytokines such as TNF-α, IL-6, and IL-1β were increased following HFD-induced diabetes." (PMID 35928902, 2022). "Elevated levels of TNF-α and IL-1B have been revealed to increase cell apoptosis and decrease fibroblast proliferation, leading to impaired wound healing in diabetes." (PMID 36484062, 2022). "Dysregulation of glucose metabolism is common in diabetes, resulting in changes in the number and type of macrophage-induced cytokines such as IL-1β, which leads to a dampening of glycolysis in macrophages in diabetic wounds." (PMID 36230913, 2022). "High levels of IL-1β, positively correlated with the severity of diabetes, confer insulin resistance in obese individuals." (PMID 36575508, 2022). "Expressions of inflammatory cytokines in the glomeruli were assessed and showed that diabetes elevated the expressions of Ccl2, Tnfa, Il1b, Adgre1 (F4/80), and Itgam (CD11b) in both PPKM2Tg and WT mice, but they were attenuated in diabetic PPKM2Tg mice." (PMID 35133981, 2022). "IL-1β and TNFα are pro-inflammatory cytokines that are expressed in common chronic pathologies such as rheumatoid arthritis, diabetes, myocardial infarction, and inflammatory lung diseases." (PMID 36101361, 2022). "The induction of diabetes increased the levels of IL-1β, IL-6, and TNF-α in the DCM model, and these effects were inhibited by PQQ." (PMID 34997266, 2022). "Overexpression of miR-93-5p in the diabetic retina alleviates the microvascular degeneration, downregulates pro-inflammatory factors (IL-1β, IL-6, and TNF-α), and elevates antioxidant levels, including GSH and superoxide dismutase (SOD)." (PMID 36292956, 2022). "The upregulation of LPS led to the expression of NLRP3 and IL-1β, thereby inducing the occurrence of diabetes." (PMID 35647057, 2022). "Mediators of inflammation—TNF-α, IL-1β, the IL-6 family of cytokines, IL-18, and certain chemokines—are believed to be involved in the etiology of diabetes." (PMID 35330193, 2022). "IL-1β was found to be increased in the retina of rats with diabetes as well as in the serum of proliferative diabetic retinopathy patients." (PMID 36582230, 2022).
diabetes (continued). "Recently, the microbiota has been reported as a link between diabetes and cancer via an IL-1β and NADPH oxidase 4 dependent signaling cascade." (PMID 36499348, 2022). "Diabetes occurs in part because the accumulation of triggered innate immune cells leads to the release of inflammatory markers, principally IL-1β and tumor necrosis factor α, that promote generalized resistance to insulin and destruction of β-cell." (PMID 35975270, 2022). "In the pathogenesis of diabetes, inflammatory factors, such as interleukin (IL)-1β, IL-8, tumor necrosis factor (TNF)-α, and induced nitric oxide synthase (iNOS), are important factors related to insulin sensitivity." (PMID 35056765, 2022). "Tai Chi intervention can reduce blood glucose, blood lipid, and insulin resistance levels and decrease the serum levels of inflammatory factors, including NF-κB, ROS, NLRP3, IL-1β, and IL-18 in pre-diabetes." (PMID 36248820, 2022). "IL-1β and IL-18 are two essential pro-inflammatory cytokines that are upregulated in tissue-resident cells of patients and animals with diabetes and are further induced by positive feedback to pyroptosis to form inflammatory storms." (PMID 36204129, 2022). "IL-1β and IL-18 have different roles in diabetes, with IL-1β contributing to type 2 diabetes by attenuating the insulin secretion function of β-cells, and IL-18 being associated with type 1 diabetes." (PMID 36232938, 2022). "High levels of IL-1β have been detected in patients with diabetes and other studies show IL-1β can affect insulin sensitivity through the TNF pathway." (PMID 35754962, 2022). "Recent clinical trials have shown potential in IL-1β blocking therapies further establishing an important role of IL-1β in progression of diabetes." (PMID 35663964, 2022). "It is noteworthy that the P13K-AKT pathway affects a variety of downstream effector molecules such as IL-6, NF-κB and IL-1β, which play an important role in the occurrence and development of diabetes through inflammatory immune response and insulin resistance." (PMID 36559019, 2022). "As diabetes is linked to cytokine-mediated inflammation leading to loss of functional β-cell mass, we next asked whether treating islets with three key cytokines (TNFα, IFNγ, IL-1β, or a cocktail of all three) affects LIM-domain complex factor expression levels." (PMID 34968409, 2022). "Early growth response 1 (Egr1) is another target gene of miR-150, and knockdown of this target alleviates the diabetes-induced inflammation in mouse mesangial cells by downregulating pro-inflammatory factors (IL-1β, IL-6, and TNF-α)." (PMID 36292956, 2022). "NLRP3 inflammasome activation is known to contribute to diabetes and dementia by triggering IL-1β maturation." (PMID 35958024, 2022). "Next, we found that ZAF, BRO and the combination of ZAF and BRO reduced the transcription and expression level of proinflammatory cytokine IL-1β and IL-6 of the hippocampus of diabetes mice, respectively." (PMID 36378718, 2022). "IL-1β was also induced in most beta cells of severely hyperglycemic diabetes-prone gerbils Psammomys obesus fed a high-energy diet which barely expressed insulin." (PMID 35629988, 2022). "The IL-1β/NF-κβ pathway is considered the “common pathways” of β cells death in types 1 and 2 diabetes." (PMID 36157449, 2022). "It has been identified as the first compound to act upstream of cryopyrin to prevent PAMPs, DAMPs, and crystal-induced IL-1β secretion and reduce IL-1β and IL-8 production by PMNs in cases of bacterial infections in patients with diabetes." (PMID 36034221, 2022). "Diabetes aggravated adverse cardiac remodeling, increased the mortality rate, cardiac hypertrophy, the fibrotic area, and enhanced IL-1β, IL-6, TNF-α, and IL-18 expression in myocardial tissue." (PMID 36320147, 2022). "In diabetes, astrocytes are upregulated at the mRNA level and secrete various pro-inflammatory cytokines, such as IL-1β and IL-6 to amplify the inflammatory response." (PMID 36016568, 2022).
diabetes (continued). "There are mechanistic links between periodontitis and other metabolic diseases, namely diabetes, which results in the production of inflammatory cytokines such as IL-1β, TNF, IL-6, as well as oxidative stress." (PMID 36013449, 2022). "It is activated under diabetes conditions that promotes caspase-1 autocleavage, and the maturation of pro-IL-1β/18, IL-1β, and IL-18 is secreted into the extracellular space to participate in the subsequent inflammatory response." (PMID 36111168, 2022). "Targeting IL-1β signaling in diabetes has been suggested and treatments targeting PDGF signaling has also been proposed for pathologies involving mesangial proliferation, for instance IgA Nephropathy7,9,57–59." (PMID 35513427, 2022). "The expression of FKN declines with diabetes progression and activates microglia in the retina, resulting in an increase in IL-1β expression in microglia and astrocytes, fibrinogen deposition, and perivascular clustering of microglia." (PMID 36016568, 2022). "NLRP3 inflammasome, IL-1β, and IL-18 can affect blood glucose control and insulin resistance, which are related to the pathogenesis of diabetes, and play an important role in diabetes-induced systemic chronic inflammation and insulin signal transduction." (PMID 36248820, 2022). "Interleukin-1β (IL-1β) is an important pre-inflammatory factor, which participates in the pathophysiological process of periodontitis and diabetes." (PMID 36430410, 2022). "During the occurrence and development of diabetes, elevated levels of glucose and free fatty acids (FFAs) stimulate islet β cells to produce IL-1β." (PMID 36430410, 2022). "The inflammatory process partly mediates vascular complications in patients with diabetes, and there is evidence that IL-1β and TNFα are the major proinflammatory mediators in cell damage and insulin resistance." (PMID 36510592, 2022). "Previously, we demonstrated that diabetes increases intestinal iNOS expression, NO levels in the portal vein, and IL-1β and TNF-α expressions in liver Kupffer cells." (PMID 35883204, 2022). "First, TNF‐α, IL‐6, IL‐1β, and IL‐18 are known to be key influential modulators of diabetes, as also cytokines which are upregulated during the systemic immune response to stroke." (PMID 35971650, 2022). "Aerobic exercise is believed to be a promising intervention to reduce the expressions of ROS, NF-κB, NEK7, NLRP3, ASC, Caspase-1, IL-1β, and other inflammatory factors, and improves diabetes-induced inflammation and reduces insulin resistance." (PMID 36248820, 2022). "Together, our study identifies a novel mechanism behind delayed wound closure in diabetes mellitus that involves IL-1β-dependent regulation of cell proliferation and migration." (PMID 34054346, 2021). "Compared with a healthy person, caspase-1 cleavage and IL-1β maturation are elevated in patients with type 2 diabetes mellitus (T2DM), which can be significantly suppressed by metformin." (PMID 33980323, 2021). "Palmitic acid (PA) is elevated in the sera of diabetics and stimulates the production of the DR-relevant cytokines by MC, including IL-1β, which induces the production of itself and other inflammatory cytokines in the retina as well." (PMID 33958662, 2021). "The potent pro-inflammatory cytokine IL-1β is known to contribute to the inflammatory response in various metabolic diseases including diabetes." (PMID 33546399, 2021). "Studies have reported that diabetes-induced gliosis eventually leads to the production and release by MGCs of inflammatory molecules such as interleukin-1β (IL-1β), interleukin-6 (IL-6), tumor necrosis factor-α (TNF-α), and chemokine ligand-2 (CCL2)." (PMID 34071438, 2021). "Previously, we have demonstrated that diabetes increases intestinal iNOS expression, NO levels in the portal vein, IL-1β and TNF-α expression of Kupffer cells in the liver." (PMID 34043673, 2021).